NBAS (NBAS subunit of NRZ tethering complex)
Description:
Involved in Golgi-to-endoplasmic reticulum (ER) retrograde transport; the function is proposed to depend on its association in the NRZ complex which is believed to play a role in SNARE assembly at the ER. Required for normal embryonic development (By similarity). May play a role in the nonsense-mediated decay pathway of mRNAs containing premature stop codons (By similarity).
Synonyms: NAG; ILFS2; SOPH
Tractability: Antibody: UniProt places it where antibodies can reach, with high confidence. PROTAC: ubiquitination databases record sites on it; its protein half-life has been measured.
Gene: Protein-coding gene on chromosome 2 (15,166,913 to 15,561,340, reverse strand). Ensembl gene ENSG00000151779.
Subcellular location: Cytoplasm; Endoplasmic reticulum; Endoplasmic reticulum membrane
Subcellular location (Human Protein Atlas): Golgi apparatus; Nuclear membrane; Nucleoli
Pathways (Reactome):
Vesicle-mediated transport: COPI-dependent Golgi-to-ER retrograde traffic
Gene Ontology:
Molecular function: protein binding; SNARE binding
Biological process: negative regulation of nuclear-transcribed mRNA catabolic process, nonsense-mediated decay; nuclear-transcribed mRNA catabolic process; retrograde vesicle-mediated transport, Golgi to endoplasmic reticulum
Cellular component: Dsl1/NZR complex; endoplasmic reticulum; membrane; cytosol; cytoplasm; endoplasmic reticulum membrane
Genetic constraint (gnomAD): Loss-of-function variants: 199 observed, 294.08 expected, observed/expected ratio (o/e) 0.68, 90% interval 0.6 to 0.76. The upper end of that interval is the gene's LOEUF score, 0.76, which puts it in group 3 of 6, group 1 being the genes least tolerant of losing a copy. Missense variants: 2,859 observed, 2,891.7 expected, observed/expected ratio (o/e) 0.99, 90% interval 0.96 to 1.02. Synonymous variants: 1,096 observed, 1,050.7 expected, observed/expected ratio (o/e) 1.04, 90% interval 0.99 to 1.1.
Homologues: Orthologues: chimpanzee NBAS (99% identical), macaque NBAS (98% identical), rabbit NBAS (90% identical), dog NBAS (89% identical), pig NBAS (87% identical), rat Nbas (86% identical), mouse Nbas (85% identical), tropical clawed frog nbas (69% identical), zebrafish nbas (64% identical), Caenorhabditis elegans smgl-1 (16% identical).
Diseases named in the same sentence as NBAS in open-access papers:
NBAS is named in the same sentence as 42 diseases in open-access papers, as found by Europe PMC text mining. Sharing a sentence is not in itself a finding about the gene and the disease. The quoted sentences say what the papers report.
acute liver failure (13 papers, 2015 to 2023). Rapid deterioration of liver function causing encephalopathy and coagulopathy. "Using whole-exome sequencing, we found that the mutation of NBAS, which is associated with recurrent acute liver failure when mutated, most likely was a potential pathogenic cause in the patient." (PMID 37055399, 2023). "Researchers in China have identified a new mutation in the gene NBAS that is associated with acute liver failure (ALF) in infants." (PMID 37055399, 2023). "In 2015, NBAS variants were linked to fever-related recurrent acute liver failure [infantile liver failure syndrome 2 (ILFS2), MIM 616483]." (PMID 34386911, 2021). "Biallelic pathogenic NBAS variants manifest as a multisystem disorder with heterogeneous clinical phenotypes such as recurrent acute liver failure, growth retardation, and susceptibility to infections." (PMID 34386911, 2021). "Biallelic mutations in the NBAS gene have been identified in recurrent acute liver failure in early infancy." (PMID 33763395, 2021). "In 2015, biallelic pathogenic variants in the neuroblastoma amplified sequence (NBAS) gene were identified as a cause of fever-triggered recurrent acute liver failure (RALF)." (PMID 34427841, 2021). "Here, we describe a case of a pediatric patient diagnosed with NBAS deficiency due to a homozygous c.2809C > G, p.(Pro937Ala) variant presenting with recurrent acute liver failure with severe hyperammonemia, acquired microcephaly and progressive brain atrophy." (PMID 34427841, 2021). "The liver phenotype in NBAS deficiency is most typically a recurrent acute liver failure, triggered by febrile infections." (PMID 31507590, 2019). "All efforts to come to a diagnosis for the causes of his recurrent episodes of liver failure had been unsuccessful, until a biallelic mutation in the NBAS gene was reported to be associated with recurrent acute-liver-failure in children." (PMID 28946922, 2017). "However, there is growing evidence that dysregulated hepatic inflammation per se can lead to acute liver failure and NBAS-deficient patients from the “β-propeller” and “Sec39” subgroup have fever-related acute liver failure." (PMID 34386911, 2021). "Another two patients with acute liver failure had a heterozygous NBAS mutation in this study." (PMID 33763395, 2021). "In conclusion, mutations in NBAS are delineated as a previously unknown cause of acute liver failure with onset in childhood triggered by febrile infections." (PMID 26073778, 2015). "We present four individuals from three families at different stages of their diagnostic trajectory with recurrent acute liver failure (RALF) and biallelic NBAS variants, confirmed by either trio analysis or cDNA studies." (PMID 35433172, 2022). "Although A330 had mutations of NBAS, it had been reported in recurrent acute liver failure without connection with leukemia so far." (PMID 36003795, 2022).
neuroblastoma (12 papers, 2013 to 2025). Neuroblastoma (NB) is the most common solid, extracranial childhood tumor. "Biallelic variants of NBAS, encoding the neuroblastoma-amplified gene protein, are linked to SOPH syndrome (MIM 614800), characterized by short stature, optic nerve atrophy, and Pelger-Huet anomaly." (PMID 34149817, 2021). "The NBAS gene was initially identified as a gene amplified in human neuroblastomas, and later found to encode a peripheral membrane protein that is a component of the Syntaxin 18 complex, with a role in Golgi-to-endoplasmic reticulum retrograde transport." (PMID 26773057, 2016). "These genes included neuroblastoma-amplified sequence (NBAS), ETS variant transcription factor 6 (ETV6), transmembrane protein 165 (TMEM165), collagen type IV alpha-3-binding protein (C43BP), serine/threonine-protein phosphatase 5 (PPP5), and short-chain specific acyl-CoA dehydrogenase (ACADS)." (PMID 39400548, 2025). "NBAS (neuroblastoma-amplified sequence) is a component of the Syntaxin 18 complex involved in Golgi-to-ER trafficking and was previously found to play a role in NMD of a subset of target mRNAs." (PMID 32635561, 2020). "The C. elegans gene smgl-1 corresponds to human NBAS (Neuroblastoma amplified sequence), also known as NAG (for Neuroblastoma amplified gene)." (PMID 26773057, 2016). "NBAS, initially identified as a gene that is co-amplified together with N-MYC in human neuroblastomas, was recently reported to encode a peripheral membrane protein that is a component of the Syntaxin 18 complex, which has a role in Golgi-to-endoplasmic reticulum retrograde transport." (PMID 23828042, 2013). "NBAS is thought to be involved in golgi-to-ER transport and is typically amplified in MYCN-amplified neuroblastoma tumors." (PMID 33245713, 2020). "The neuroblastoma-amplified gene (NAG), alternatively called neuroblastoma-amplified sequence (NBAS), was first identified as a gene co-amplified with the MYCN gene in neuroblastoma." (PMID 25364732, 2014). "NBAS was first identified as a gene that is coamplified with the N-myc gene in human neuroblastomas; however, no clear role in the disease has been reported." (PMID 32616520, 2020). "NBAS, also known as the neuroblastoma amplified gene (NAG), is a large gene comprising 52 exons and is mapped to chromosome 2p24.3, which was originally identified as frequently co-amplified with N-myc in neuroblastomas." (PMID 33042920, 2020).
optic atrophy (9 papers, 2013 to 2026). A disorder characterized by loss of optic nerve fibers. "Previously, the mutations within the NBAS were reported to be the cause of short stature, optic atrophy and Pelger-Huët anomaly of granulocytes (SOPH) syndrome in an isolated Russian yakut population." (PMID 32957979, 2020). "Recently, a single point mutation in the NBAS gene was shown to cause a human syndrome with short stature, facial dysmorphism, optic atrophy and leucocytes anomaly, termed, SOPH." (PMID 23828042, 2013). "Biallelic variants in the neuroblastoma amplified sequence (NBAS) gene have been associated with short stature, optic atrophy, and Pelger-Huët anomaly (SOPH) syndrome, infantile liver failure syndrome type 2 (ILFS-2), and an increasingly broad spectrum of clinical phenotypes." (PMID 42305553, 2026). "Fundus changes in patients with variants in seven genes exhibited optic atrophy plus retinal degeneration in our in-house cohort, including ACO2, FDXR, NBAS, OPA3, RTN4IP1, SSBP1 and C12ORF65." (PMID 39423307, 2025). "Many studies reported that NBAS gene mutations were associated with infantile failure syndrome 2 (ILFS2), a fever-induced multi-systemic syndrome known as short stature with optic atrophy and Pelger-Huët anomaly (SOPH) syndrome, and immunodeficiency." (PMID 40370974, 2025). "The causative variants in PTPN23, TMEM126A, NBAS, and WFS1 genes were identified in 4 probands with a recessive form of optic atrophy." (PMID 36071901, 2022). "Increasing research has reported that the phenotype spectrum of NBAS mutations ranges from isolated ILFS2 to a multi-systemic disease including short stature, skeletal dysplasia and optic atrophy." (PMID 32957979, 2020). "Among the cases of recessive optic atrophy, there was one case of short stature, optic nerve atrophy, Pelger-Huet anomaly (SOPH syndrome) caused by NBAS variants, one case of PTPN23 optic atrophy syndrome, one case of TMEM126A optic atrophy, and one case of Wolfram syndrome." (PMID 36071901, 2022). "None of the patients in our case series of individuals with NBAS‐related RALF had a variant in the C‐terminal domain, which is more commonly associated with short stature, optic atrophy, and Pelger‐Huët anomaly." (PMID 35433172, 2022).
SOPH syndrome (9 papers, 2013 to 2025). "Specifically, SOPH syndrome is typically linked to variants in the C-terminal region of the NBAS protein, whereas ILFS2 is predominantly associated with variants affecting the Sec39 domain." (PMID 41132786, 2025). "NBAS is known to cause SOPH syndrome and PLS3 are known to be associated with heritable bone fragility but autism is not a known association with these genes." (PMID 29955634, 2018). "Of particular interest, a mutation in the NBAS gene has been reported in a hereditary short stature syndrome (SOPH syndrome) in the Yakuts population that lives in the far east of the Russian Federation." (PMID 23828042, 2013). "Moreover, variants located in the β-propeller domain of NBAS may lead to a mixed multisystem phenotype exhibiting features of both ILFS2 and SOPH syndrome." (PMID 41132786, 2025). "Neither NBAS mutation had been previously reported in cases of ILFS type 2 or SOPH syndrome." (PMID 30622725, 2019). "Importantly, individuals with SOPH syndrome were not reported to have ALF or any hepatic disease manifestation and the impact of the SOPH-associated mutation on NBAS protein function is unknown." (PMID 26073778, 2015).
liver failure (6 papers, 2017 to 2025). A liver disease characterized by the liver losing or has lost all of its function. "Mutations in NBAS were first identified as an important cause of infantile and later-onset recurrent liver failure in 2015." (PMID 28629372, 2017). "A liver biopsy can be performed to determine whether there is fibrosis in the liver and the expression of NBAS protein, to reduce the occurrence of postoperative complications and avoid the recurrence of postoperative liver failure." (PMID 40370974, 2025). "Thus, our results suggest a convergent disease etiology for optic nerve atrophy, muscular hypotonia, neurodevelopmental delay, and liver failure phenotypes observed in RINT1- and NBAS-deficient patients." (PMID 37463447, 2023).
Pelger-Huet anomaly (6 papers, 2018 to 2023). An autosomal dominant inherited condition caused by mutations in the lamin B receptor gene. "Mutations in NBAS are associated with Pelger-Huet Anomaly, which has a phenotype including facial asymmetry, long face, and straight nose." (PMID 30631343, 2018).
liver disease (5 papers, 2015 to 2025). "Therefore, it is expected that mutations of the NBAS N-terminus, as well as C-terminus affect its function and might cause liver disease in patients." (PMID 33042920, 2020). "While heterozygous carriers of ABCB4 are prone to develop liver disease, the role of heterozygous NBAS is not well known." (PMID 40870862, 2025). "Further investigations using the patient’s iPS cell-derived hepatocytes will show whether the episodes of liver disease are due to alterations in Golgi-to-ER retrograde vesicular trafficking and/or impaired nonsense-mediated mRNA decay, or a yet-to-be-discovered NBAS function." (PMID 30622725, 2019). "NBAS had earlier been implicated in the developmental disorder SOPH syndrome, in which liver disease is not a feature." (PMID 28629372, 2017).
Immunodeficiency (3 papers, 2020 to 2024). Failure of the immune system to protect the body adequately from infection, due to the absence or insufficiency of some component process or substance. "In conclusion, NBAS variants cause a multisystem disease including an immunodeficiency phenotype marked by low NK cell numbers and NK cell dysfunction as well as reduction of naïve B cells and serum immunoglobulin levels." (PMID 34386911, 2021). "According to multisystem phenotype, NBAS-deficient patients are followed by various specialists, it is important that these patients are referred to immunologists early to be screened for immunodeficiencies." (PMID 33042920, 2020). "We performed a literature review of NBAS gene-associated cases with immunodeficiency or HLH." (PMID 39429260, 2024).
Brain atrophy (2 papers, 2021 to 2023). Partial or complete wasting (loss) of brain tissue that was once present. "Since then, additional patients with NBAS deficiency displaying neurologic features including motor delay, muscular hypotonia, intellectual disability, and brain atrophy have been reported." (PMID 37463447, 2023). "Since then, some patients with NBAS deficiency presenting with neurologic features, including a motor delay, intellectual disability, muscular hypotonia and a mild brain atrophy, have been reported." (PMID 34427841, 2021). "The presence of an acquired and progressive microcephaly with brain atrophy in our patient raises the hypothesis about a primary neurologic phenotype in NBAS deficiency." (PMID 34427841, 2021).
hemophagocytic lymphohistiocytosis (2 papers, 2022 to 2025). "This article reports a case of a child with NBAS gene variant combined with Epstein–Barr virus (EBV)-associated hemophagocytic lymphohistiocytosis (HLH)." (PMID 40894400, 2025).
osteogenesis imperfecta (2 papers, 2018 to 2020). Osteogenesis imperfecta (OI) comprises a heterogeneous group of genetic disorders characterized by increased bone fragility, low bone mass, and susceptibility to bone fractures with variable severity. "The next most frequent feature of NBAS deficiency was bone anomalies, which were reported in more than 90% of the patients, including severe osteogenesis imperfecta in 8 patients." (PMID 33042920, 2020). "Mutations in another component NBAS, are linked to dysregulated collagen secretion in atypical osteogenesis imperfecta." (PMID 29513218, 2018).
Achalasia (1 paper, 2021). A disorder of esophageal motility characterized by the inability of the lower esophageal sphincter to relax during swallowing and by inadequate or lacking peristalsis in the lower half of the body of the esophagus. "The two consanguineous siblings (individuals 11 and 12) share, besides the homozygous VUS in SETD1B, also homozygous VUS in NBAS (associated with immune defects) and NOS1 (associated with achalasia)." (PMID 34345025, 2021).
acute infantile liver failure (1 paper, 2015). "The detection rate of NBAS mutations in random individuals with (recurrent) acute infantile liver failure was very high (6 out of 15 screened individuals), so NBAS deficiency might be a frequent cause of not only RALF but also isolated ALF at least in children." (PMID 26073778, 2015). "RALF due to mutated NBAS is a presumably relatively frequent inherited cause of RALF, because NBAS screening of 15 individuals with RALF or acute infantile liver failure resulted in the discovery of six affected individuals from five additional families." (PMID 26073778, 2015).
infantile liver failure syndrome (1 paper, 2022). "NBAS is associated with infantile liver failure syndrome, short stature and optic nerve atrophy." (PMID 35045821, 2022).
leukopenia (1 paper, 2026). "We identified novel compound heterozygous variants in the NBAS gene, c.5139-5T>G and c.5983C>T, in a Chinese girl who successively developed recurrent infections, short stature, ILFS-2, progressive cytopenias from leukopenia to bicytopenia and eventually pancytopenia, and HLH." (PMID 42305553, 2026).
liver fibrosis (1 paper, 2025). "The results indicated that the donor was carrying the c.3596G>A (p.C1199Y) mutation, with normal levels of NBAS protein and without liver fibrosis." (PMID 40370974, 2025).
meningioma (1 paper, 2020). A generally slow growing tumor attached to the dura mater. "NBAS, TIMP2, and NCK1 were few of the key proteins found to be altered in Atypical meningiomas." (PMID 32974197, 2020).
skeletal dysplasia (5 papers, 2018 to 2021). Any Mendelian diseases that affects growth and development of the skeleton. "Increasing evidence has indicated a phenotypic spectrum of NBAS mutation-based disease, from isolated fever-triggered recurrent ALF to a multisystemic disease with short stature, skeletal dysplasia, immunological abnormalities, and optic nerve atrophy resembling SOPH syndrome." (PMID 30622725, 2019).
tumor (3 papers, 2020 to 2025). "No recurrent fusion has been reported in NB, with the exception of fusions including the NBAS gene in MYCN-amplified tumours." (PMID 33172452, 2020). "MYCN-MB fusion transcripts were unique to each tumor; 2 recurrent fusion-partner genes, DDX1 and NBAS (immediately upstream of MYCN41) were involved in fusions with each other and additional partners (MYCNOS) in 3 MYCN-MBGrp3/4 tumors, but fusion position and gene order were not conserved." (PMID 39377358, 2025).
infection (1 paper, 2023). The state of being infected such as from the introduction of a foreign agent such as serum, vaccine, antigenic substance or organism. "To answer this question, we assessed NBAS expression and function in the NMD pathway and Golgi-to-ER transport, and key players of these cellular mechanisms, in SARS-CoV-2-infected Calu3 cells, which are an established in vitro model of infection relevant to human pathology." (PMID 36768954, 2023). "Co-localization of NBAS and UPF1 proteins did not change within 24 h of infection nor did it differ in infected versus non-infected cells at 1 and 24 h after infection; similarly, the co-localization of NBAS and p31 proteins was not altered by infection in this short time frame." (PMID 36768954, 2023).
NBAS also shares sentences with these, for which no sentence is quoted: infantile liver failure syndrome type 2 (4 papers); cancer (2); mitochondrial disease (2); autism (1); autoimmune hemolytic anemia (1); B cell deficiency (1); bacterial infections (1); cervical cancer (1); Cirrhosis (1); coagulopathy (1); endocrine disorders (1); gastrointestinal stromal tumours (1); Hyperammonemia (1); infantile liver failure syndrome type 1 (1); Intellectual disability (1); leukemia (1); microcephaly (1); middle ear infections (1); pneumonia (1); retinal degeneration (1); Thrombocytopenia (1); Wolfram syndrome (1).